TNF (tumor necrosis factor)
Diseases named in the same sentence as TNF in open-access papers (continued):
Sharing a sentence is not in itself a finding about the gene and the disease.
cancer (continued). "Additional cancer-related pathways that appear to be altered following CaSm induction include transforming growth factor-β, tumor necrosis factor and vascular endothelial growth factor, which are known to contribute to EMT/metastasis, cachexia and angiogenesis, respectively." (PMID 26751936, 2016). "TNF-α, mainly secreted by macrophage, is a key player in cancer-related inflammation." (PMID 26992854, 2016). "This network also includes accepted cancer markers, such as TNF, STAT3, NF-κB and IL6." (PMID 27685442, 2016). "It has been reported that Smac mimetics induce TNFα-dependent cancer cell death by targeting IAPs." (PMID 27737687, 2016). "In cancer cells, TNF has also been described as a regulator of glycosphingolipid expression." (PMID 27916834, 2016). "Previous studies showed that zVAD-fmk and IAP antagonist could induce necroptosis in cancer cells that was dependent on autocrine TNFα production." (PMID 25575821, 2015). "Indeed, extracellular signaling of FGF10, VEGFC, IL10 and TNFα of AMSCs was dramatically induced when they were co-cultured with cancer cells, and these molecules are suggested to have a direct or indirect impact on Wnt signaling pathway." (PMID 26060426, 2015). "TNF has both inducing and protective roles during cancer development." (PMID 25807548, 2015). "In this contest, TNFα seems to play an important role as enhancer of the B16 cancer cells activity." (PMID 26264809, 2015). "Activation of TNF-α production by N-BPs may be beneficial, as certain malignant tumours are sensitive to this cytokine." (PMID 25588705, 2015). "However, the combined treatment of lovastatin and gefitinib increased the expression of TNF-α mRNA compared with that of the signal agents in both cancer cell lines." (PMID 26160843, 2015). "These cells activate NF-κB in response to TNFα and to some cancer chemotherapeutic drugs." (PMID 26063116, 2015). "Flagellin governs the proliferation of T cells and cancer cells by upregulating cytokines and chemokines, including TNF-α and IL-6, and the role of mTOR signaling in flagellin-induced inflammatory responses is unknown." (PMID 25942007, 2015). "Given that TNFα is able to upregulate Fas expression in human cancer cell lines and sensitize them to FasL-induced cell death, we sought to investigate whether TNFα and FasL combination could be therapeutically relevant in NBL." (PMID 25890358, 2015). "Adipose tissue secrete TNF-α leading to inflamation promoting cancer." (PMID 25923423, 2015). "First, N-6 strongly inhibited TNFα-induced AKT activation in cancer cells." (PMID 26156677, 2015). "However, the results regarding the role of TNF-α in cancer are controversial; high concentrations of this cytokine induced an antitumoural response in a murine model of sarcoma." (PMID 26508818, 2015). "Decursin and decursinol angelate from A. gigas inhibit not only NO production and NO-induced inflammation by suppressing MMP-9, iNOS, IL-1β, and TNF-α expression but they also demonstrate anti-cancer effects by inhibiting cell proliferation and activating apoptosis." (PMID 26083119, 2015). "TNF-α is one of the important inflammatory cytokines that can promote cancer metastasis." (PMID 26631692, 2015). "Increased production of lipolytic factors from adipose tissue such as tumor necrosis factor alpha (TNFα) or zinc-a2 glycoprotein (ZAG) could explain the increased lipolysis in cancer cachexia." (PMID 26098097, 2015). "There is therefore a need that physicians treating patients affected with inflammatory rheumatisms with TNF blockers recognize malignant skin lesions, requiring an urgent referral to the dermatologist and a potential withdrawal or modification of the immunomodulatory treatment." (PMID 25996152, 2015). "Furthermore, in post-chemotherapy cancer patients, increased TNF-α is observed in addition to enhanced TNF-related apoptosis." (PMID 26303743, 2015).
cancer (continued). "Interestingly, treatment with tumor necrosis factor (TNF)-related apoptosis inducing ligand (TRAIL) also induces membrane calreticulin exposure on cancer cells." (PMID 25750898, 2015). "While an autocrine/paracrine TNFα loop has been demonstrated to mediate cell death in response to Smac mimetics alone and in combination with chemotherapeutic drugs in a variety of cancers, in our present study TNFα turned out to be dispensable for both DOX/BV6- and VCR/BV6-mediated apoptosis." (PMID 26575016, 2015). "Furthermore, there is still some controversy in the literature, related to the role of ghrelin, ANGPT4, HIF-1, and TNF-α in cancer cachexia and metastasis development, indicating the necessity of more studies." (PMID 26508818, 2015). "TNF-α is a critical pro-inflammatory cytokine, which is involved in cancer progression." (PMID 25435993, 2015). "The rare localization of this cancer could suggest a possible linkage of the malignancy to the chronic intake of anti-TNF-α treatment." (PMID 25815013, 2015). "In addition, the most sensitive pathways reported here for furan involve cell death-, Tumor Necrosis Factor (TNF)-, and cancer-related processes, all of which are relevant to furan’s MoA." (PMID 26313361, 2015). "TNFα is deemed consistently to stimulate NFκB activation in different cancer cells." (PMID 25704885, 2015). "Furthermore, a recent study showed that the combined action of TNFα and IFNγ is necessary for the control of a range of murine and human tumors by driving cancer cells into senescence." (PMID 26635798, 2015). "Monocytes, known as the key component of inflammation system, might directly stimulate cancer cell growth by producing various proinflammatory cytokines, such as interleukin-1, interleukin-6, and tumor necrosis factor." (PMID 25994571, 2015). "Treatment of lymphocytes with IL-32 may induce the expression of different cytokines, including tumor necrosis factor (TNF)-α or IL-8, which have been found to be involved in multiple inflammatory processes and cancer progression." (PMID 25435980, 2015). "Exposure to exogenous TNFα can induce ICAM1 in cancer cells." (PMID 25879517, 2015). "Upregulation of NF-κB by TNF exposure confers increased radiation resistance to cancer cells." (PMID 26569225, 2015). "Second, N-6 and TNFα synergistically induced caspase-8 activation and cancer cell apoptosis." (PMID 26156677, 2015). "The suppression of M2-induced IL-10, IL-12, and TNF-α secretion was observed during the transition from inflammatory hyperplasia to carcinoma, but these cytokines were again expressed at high levels during metastasis, which was concordant with the mRNA expression data." (PMID 25434400, 2015). "In addition, some studies have reported that a substitution G/A at –308 position of TNF-α gene promoter is correlated with cytokine production and increased cancer risks." (PMID 26019577, 2014). "The results above suggested that Bregs could promote cancer growth and the secretion of TNF-α might lead to the generation and accumulation of Bregs in cancer." (PMID 24991577, 2014). "Cytokines like TNF-α are the mediators that link inflammation and cancer." (PMID 24809702, 2014). "To determine whether the endogenous TNF-α promotes cancer cell proliferation, we first treated the human SGC-996 cells with siRNA directed against TNF-α." (PMID 24676340, 2014). "Thus, the anti-cancer activities of TNF-α are enhanced when combined with the natural proteasome inhibitors, WA or Cel." (PMID 25419573, 2014). "In order to prove that the blockage of TNFα signaling could be considered for cancer patients treated with IL-12, we must demonstrate that abrogation of TNFα does not affect the powerful antitumor capacity of IL-12." (PMID 24587231, 2014).
cancer (continued). "During a 16114.16 patient-years follow-up, the RR and IRR for developing a malignancy in both methotrexate- and anti-tumor necrosis factor (TNF) biologics-naïve JIA children were 2.75 (95% confidence interval, 1.75 – 4.32) and 3.21 (2.01 – 5.05), respectively." (PMID 25174953, 2014). "TNF-α can promote cancer cell proliferation and invasion and it is mainly produced by macrophages." (PMID 24676340, 2014). "However, the US Food and Drug Administration (FDA) recently issued an alert to healthcare professionals that its analysis has revealed that 48 children developed malignancies whilst on anti-TNF agents, and 11 of the children died." (PMID 24405833, 2014). "We aimed to compare the relative risk of cancer development between RA patients taking tumor necrosis factor α (TNFα) antagonists and those taking nonbiologic disease-modifying anti-rheumatic drugs (nbDMARDs)." (PMID 25267341, 2014). "In addition, the expression of MMP-2, MMP-9, and TNF-α genes is significantly reduced in melanoma recovered from RET mice treated with HB-19: HB-19 seems to have potential for cancer treatment and prevention." (PMID 24469254, 2014). "In cancer models, G-MDSCs can be differentiated from immunosuppressive to immunogenic TNF-alpha secreting neutrophils after intra-tumoral injection of attenuated Salmonella vaccine, and therapeutic vaccination to cancer antigens is restored after in vivo depletion of MDSC." (PMID 25248150, 2014). "Based on this experimental model of TNF-α-mediated inflammation and high-throughput gene expression data, they also developed a prognostic gene signature that predicted overall survival in human cancers." (PMID 25548907, 2014). "Indeed this is the case in many cancer cells that are subject to pro-apoptotic stimuli where survival pathways, such as the nuclear-factor kappa B (NF-κB), are activated in response to TNF-α." (PMID 24690670, 2014). "Given that flavonoids also have anti-cancer properties, luteolin could be used together with anti-TNF agents both for potential synergism and for protection against the cancer-inducing side effects of such agents." (PMID 24587411, 2014). "In addition to its role in inflammation, TNF-α can significantly modulate the proliferation, differentiation, and cell death of colonocytes during cancer progression." (PMID 24876678, 2014). "TNFα originally identified as a mediator of inflammatory responses with cytotoxic functions, was recognized more recently as a potential inducer of cancer progression by promoting growth and metastatic dissemination of cancer cells in autocrine and paracrine manner." (PMID 24626571, 2014). "Because drugs such as anti-cancer or anti-tumor necrosis factor-α may exacerbate pre-existing IP, there was concern that administration of PC-SOD would induce AE of IP." (PMID 24886036, 2014). "TNF-α is also frequently found overexpressing in many human cancer tissue." (PMID 25203554, 2014). "Our next study will focus on validation of these candidate genes filtered out in both nmMLCK and TNFα studies and generate a more accurate cancer prognosis platform with a refined gene set, which will lead to the development of cancer risk prediction/prognosis gene array in clinical trials." (PMID 24714365, 2014). "We first enriched the literature derived interactome of six phosphatases and two phosphatase accessory subunits by affinity purification experiments of phosphatase complex followed by quantitative mass spectrometry based proteomics in cancer cells stimulated with TNFα." (PMID 24847354, 2014).
cancer (continued). "TNF-α has been shown to support cancer cell proliferation, angiogenesis, and metastasis." (PMID 25019059, 2014). "TNF-alpha is a key cytokine involved in inflammation and cancer, and is known to induce EMT." (PMID 24912499, 2014). "The association between TNF-α antagonists and cancer risk was independent of daily dosage of concomitant nbDMARDs." (PMID 25267341, 2014). "Furthermore, we provide evidence that regulation of PAR-4 through its hydrolysis by caspase-8 during TNFα-induced apoptosis is an essential step for the induction of cell death in some cancer cells." (PMID 24931006, 2014). "Here, we aimed to compare the cancer risk among RA patients starting TNFα blocker and those taking nonbiologic disease modifying antirheumatic drug (nbDMARD) in a large cohort of patients with RA, based on a Taiwanese nationwide database." (PMID 25267341, 2014). "Based on the ability of TNF-α to activate an apoptotic response, it seemed likely that one mechanism by which cancer cells may act to evade TNF-α induced apoptosis would be to counter balance this response by inducing pro-survival factors such as 14-3-3ζ." (PMID 24690670, 2014). "Analogous to Theileria-induced host cell transformation, MAP4K4 signaling might be relevant in driving cancer cell dissemination in tumors, where increased levels of anti-cancer therapy-induced TNFα has been noted in the surrounding stroma." (PMID 24626571, 2014). "However, most studies into the mechanisms of inflammation-driven metastasis have focused on the induction of chemokine receptors, which can direct the movement of cancer cells, by inflammatory cytokines such as TNF-α, IL-1β and IL-6." (PMID 24789104, 2014). "Compared to the lowest risk group (high 25OHD and low TNFα levels), patients in the highest risk group (low 25OHD and high TNFα levels) had more than 7-fold increased odds of ER negative vs. ER positive cancer (OR = 7.32, 95% CI = 2.44–21.98)." (PMID 24473087, 2014). "One large meta-analysis including 22.904 patients treated with different TNF-α-inhibitors only found an increased risk of nonmelanoma skin cancer but no increased risk of other cancers." (PMID 23762724, 2013). "Adhesion molecules play a major role in the step involving the attachment of the free cancer cells to the peritoneal surface and cytokines, such as interleukin 1ß (IL1ß) and tumor necrosis factor α (TNFα) released in the inflammatory microenvironment, are known to promote their expression." (PMID 23451255, 2013). "Because TOV-21G cells highly express CXCL12/CXCR4 and CXCL16/CXCR6 axes in spite of a low response to EGF or TNF, these axes may contribute to cancer progression as described by others." (PMID 23800251, 2013). "Here, we showed that Ssd significantly potentiated TNF-α-mediated cell death in HeLa and HepG2 cancer cells via suppression of TNF-α-induced NF-κB activation and its target genes expression involving cancer cell proliferation, invasion, angiogenesis and survival." (PMID 23573150, 2013). "Likewise, AIMs significantly inhibited cancer cell migration in the wound healing test, but the antimigratory effect of AIMs was also diminished by TNF." (PMID 23864892, 2013). "TGF-β, considered an immunosuppressive cytokine, reduces numbers of NK CD56(dim) cells, inhibits production of IFN-γ and TNF-α in vitro and is now considered important in facilitating immune evasion in a cancer microenvironment through suppression of cytotoxic lymphocytes." (PMID 23957956, 2013).
cancer (continued). "The in vivo effects of TNF have been well characterized both in pre-clinical models and in humans undergoing isolated limb perfusion, a regional cancer therapy used to deliver high doses of a drug into the bloodstream of a limb avoiding severe systemic side effects." (PMID 24062984, 2013). "We recently reported that the chloroform, but not hexane or methanol fractions from C. anthelminticum (L.)seeds (CACF) exhibited anti-oxidant property by inhibiting tumor necrosis factor-α (TNF-α)-induced human cancer cell growth by interrupting the activation of nuclear factor-kappa B (NF-κB)." (PMID 23437193, 2013). "TNF-alpha (TNFα) has “yin and yang” roles in cancer development and metastases." (PMID 23818931, 2013). "We therefore investigated whether GMF decreases the enhancement of TNF-α on the biologic events of cancer progression." (PMID 24386633, 2013). "Although evidence supports the theory that tumor necrosis factor (TNF)-related apoptosis-inducing ligand (TRAIL) is a promising candidate for treating cancer, its usage may be limited due to the resistance to the TRAIL-induced apoptosis of cancer cells." (PMID 24137422, 2013). "In addition, currently, there is no research which has been reported using CD gene combined with TNF-α gene in treating cancer." (PMID 23593411, 2013). "TNF-α-mediated the killing of certain cancer cells has been demonstrated." (PMID 24066693, 2013). "The activation of survival pathway renders most cancer cells resistant to TNF-induced cytotoxicity." (PMID 24146961, 2013). "However, when asked about cancer screening in the UK, nobody identified this as particularly important for themselves because they take anti-TNF." (PMID 23663548, 2013). "However, its undesirable responses of TNF-α on activating NF-κB signaling and pro-metastatic property limit its clinical application in treating cancers." (PMID 23573150, 2013). "In order to investigate whether apoptosis is involved upon the treatment of Ssd and TNF-α, we determined the mitochondrial membrane potential (ΔΨm) in HeLa cancer cells using live-cells imaging with JC-1 dye." (PMID 23573150, 2013). "Here, we for the first time revealed that the combined treatment with Ssd and TNF-α could significantly potentiate cell death in HeLa and HepG2 cancer cells which are insensitive to TNF-α treatment alone." (PMID 23573150, 2013). "Overexpression of CK2 in cancer cells protects cells from etoposide- and diethylstilbestrol-induced apoptosis, resulting in suppressed apoptosis mediated through tumor necrotic factor-alpha (TNF-α), TRAIL and Fas L, and augments apoptosis in cells sensitive to these ligands." (PMID 23845105, 2013). "Epidemiological data also supported the role of IL-6 and TNF-α in cancer promotion." (PMID 24205276, 2013). "The novel cellular mechanisms mediating IL-15 nuclear export and secretion in response to TNF may have broad clinical implications for inflammatory diseases and cancer." (PMID 23950892, 2013). "Further, we have shown that treatment of cervical (HeLa), ovarian, (PA-1) and thyroid (WRO) cancer cells devoid of expression of the endogenous MADD are more susceptible to both spontaneous and TRAIL- and TNFα-induced apoptosis, primarily through the activation of the extrinsic apoptotic pathway." (PMID 23457619, 2013). "Therefore, TNF is a good therapeutic target for treatment of inflammatory disorder as well as cancer to reduce proinflammatory response." (PMID 23864892, 2013). "In the current study, we concluded that Ssd effectively inhibits proliferation, suppresses invasion, abrogates angiogenesis, and induces apoptosis in cancer cells through the downregulation of TNF-α-mediated NF-κB signaling and its dependent oncogenic genes expression." (PMID 23573150, 2013).